METTL3 (methyltransferase 3, N6-adenosine-methyltransferase complex catalytic subunit)
Diseases named in the same sentence as METTL3 in open-access papers (continued):
Sharing a sentence is not in itself a finding about the gene and the disease.
cancer (continued). "For instance, METTL3, besides having methyltransferase activity, can enhance the translation of cancer genes and affect the progression of tumors independently of their catalytic subunits." (PMID 35053496, 2022). "The immunohistochemistry was used to analyze the difference of METTL3 expression between cancer tissues and adjacent normal tissues." (PMID 36058919, 2022). "Abnormal expression of METTL3 in various cancers played a dual part in the infiltration of immune cells." (PMID 36517820, 2022). "This review compiles and discusses the current literature regarding the diverse functions of METTL3 in cancer." (PMID 36008936, 2022). "The biological functions of METTL3 have been widely studied to be involved in different aspects of cancer development." (PMID 35287752, 2022). "Many pathways involved in cancer were identified to be enriched by genes when METTL3 is depleted, including genes involved in the PCa KEGG pathway, such as TMPRRS2 and KLK3." (PMID 36291932, 2022). "Ribonucleic acid (RNA) N6-methyladnosine (m6A) and methyltransferase-like 3 (METTL3) play key roles in cancer progression." (PMID 35012593, 2022). "Ebv-circRPMS1 binds to Sam68 to promote its physical contact with the METTL3 promotor, resulting in transactivation of METTL3 and development of cancer." (PMID 36386850, 2022). "Recent studies of METTL3 and METTL14 in cancers have shown that they are closely associated with the processes involved in the proliferation, apoptosis, metastasis, and differentiation in the progression of various human cancers." (PMID 35455436, 2022). "Meanwhile, METTL3 has been shown to promote translation of a large subset of oncogenic mRNAs, thereby promoting growth, survival and invasion of cancer cells." (PMID 36289222, 2022). "By increasing the modification of m6A, METTL3 plays a crucial role in the oncogenesis of several cancers." (PMID 35804965, 2022). "Using the gene expression profiling interactive analysis (GEPIA) database, METTL3 was found to be abnormally expressed in a wide range of malignant tumors, including CCs." (PMID 35255776, 2022). "Several studies reported that that METTL3 is upregulated in many cancer types including adenocarcinoma of lung that stimulates the growth of cancer cells." (PMID 35571490, 2022). "First, we confirmed increased expression of PLK1 in the Beta/Duct/Cancer cluster due to increased METTL3 expression." (PMID 35773310, 2022). "METTL3 expression levels were higher in patients in later stages of ACC and KICH; however, the expression levels of METTL3 in patients with LIHC with stage IV cancers were significantly lower than those in patients with LIHC at earlier stages." (PMID 36614956, 2022). "Among these cell populations, we analyzed the clusters overexpressing METTL3 and recognized as cancer (Beta/Duct/Cancer) and the surrounding clusters recognized as normal pancreatic ducts (Duct-1, Beta/Duct-1)." (PMID 35773310, 2022). "Research shows that METTL3 is mainly expressed as an oncogene in digestive system cancer but that METTL14 plays a role in inhibiting cancer." (PMID 35484099, 2022). "WTAP expression is regulated by METTL3, with its oncogenic function in some cancer types found to be related to its m6A methyltransferase complex function." (PMID 36733939, 2022). "The overexpression of METTL3 in different types of cancer promotes the m6A modification of pri-miRNAs, which leads to the upregulation of mature oncomirs: miR-1246, miR-25-3p, miR-221/222, miRNA-92 and miR-126-5p." (PMID 36012529, 2022). "METTL3 inhibitors, such as UZH1a, have a good potential for the treatment of METTL3-related cancers." (PMID 35692393, 2022). "We further found that METTL3 and ARHGAP5 mRNA and protein levels were significantly decreased in ADAR1-loss cancer tissues compared to the Ctrl sgRNA group." (PMID 36077054, 2022).
cancer (continued). "Recent studies have indicated that the m6A modification and METTL3 play important roles in the progression and chemotherapy response of various cancers, including BC." (PMID 35502895, 2022). "Targeted demethylation of PDK4 mRNA by dm6A-CRISPR reversed METTL3-induced PDK4 expression and lactate production, implying that METTL3 is a driver of aerobic glycolysis in cancer cells." (PMID 36289851, 2022). "Our in vitro and in vivo data revealed that regulation of the METTL3-m6A-CDC25B axis resulted in the adjustment to the proliferation of cancer cells." (PMID 35637959, 2022). "Many reports have revealed that METTL3 contributes essentially to cancer progression and presents an important mechanism of epigenetic alteration in human carcinogenesis." (PMID 35794583, 2022). "METTL3 a potential oncogene exaggerates several cancers progression, including hematopoietic malignancies." (PMID 35571490, 2022). "It was observed that CDON, YTHDF1 and METTL3 were highly expressed in cancer tissues compared to that of in corresponding normal tissues, suggesting that there was a positive relationship between FRAS1, CDON, and METTL3/YTHDF1." (PMID 36008805, 2022). "Previous studies suggest that diverse signals and pathways in cancers are regulated by METTL3, including cell proliferation, invasion, metastasis, and drug resistance." (PMID 35197058, 2022). "The immune checkpoint genes TNFRSF25 and ADORA2A were positively correlated with METTL3 expression in most cancer types." (PMID 36614956, 2022). "While there is evidence supporting a role for aberrant METTL3 in many cancer types, including localised PCa, the wider contribution of METTL3, and by inference m6A, in androgen signalling in PCa remains poorly understood." (PMID 36291932, 2022). "As two major components of the m6A MTC, METTL14 and METTL3 have recently been reported to play roles in malignant tumors." (PMID 35538475, 2022). "Given the important role for m6A in transcription and translation and evidence implicating METTL3 in many cancer types, bioinformatic analyses of publicly available clinical genomic datasets was undertaken to understand the role of METTL3 in PCa." (PMID 36291932, 2022). "Everolimus is an mTOR inhibitor that targets PTEN and TMEM127, and the resultant inhibitory effect is more pronounced in cancers with high METTL3 expression, albeit small molecule inhibitors of METTL3 are currently under investigation." (PMID 36561529, 2022). "The METTL3 RNA-m6A methyltransferase has been reported to be involved in the development and progression of many cancer types, including PCa." (PMID 36291932, 2022). "METTL3, through its methyltransferase activity, influences several biological processes and plays multiple roles in cancers." (PMID 35197058, 2022). "In LIHC and PAAD, the number of immune checkpoint genes significantly positively correlated with METTL3 expression, which was the highest among different cancers." (PMID 36614956, 2022). "We also revealed that METTL3 inhibited the infiltration of immune cells, playing an immunomodulatory role in HPV-associated cancers." (PMID 35813476, 2022). "Recently, RNA m6A modification and the core RNA methyltransferase, METTL3, were reported to play an important role in cancer chemotherapy." (PMID 35502895, 2022). "Most m6A methyltransferases and demethylases have been intensively investigated in cancers, such as METTL3, METTL14, FTO, and ALKBH5." (PMID 35596159, 2022). "Current research on m6A involvement in cancer angiogenesis has mainly focused on an m6A writer METTL3; hence, future studies on other m6A regulators are required in the near future." (PMID 35409166, 2022). "METTL3 has been reported to be involved in the progression of several types of cancers, including BC." (PMID 35502895, 2022). "The most well-studied m6A methyltransferase, METTL3, plays critical roles in regulating gene expression and affecting the outcome of various cancers." (PMID 36008936, 2022).
cancer (continued). "N6-methyladenosine (m6A) RNA methylation and its methyltransferase METTL3 have been widely reported to be involved in different cancers by regulating RNA metabolism and function." (PMID 35287752, 2022). "We next explored the mRNA expression of METTL3 in various cancer cell lines using the CCLE database." (PMID 36614956, 2022). "We find predominantly cytoplasmic METTL3 expression inversely correlates with node metastasis in human cancers." (PMID 36289222, 2022). "Previous studies reported that METTL3 and 14 act as oncogenes in several types of cancer by regulating DRG1 and MYC, respectively." (PMID 35794212, 2022). "Inhibition of METTL3 in tamoxifen-resistant cancer cells can lead to the decrease of AK4, which further promotes the apoptosis of mitochondrial, thus attenuates resistance to tamoxifen." (PMID 35022030, 2022). "The results suggest that METTL3 mainly acts as an oncogene and can serve as a prognostic biomarker in pan-cancer." (PMID 36614956, 2022). "In this cancer, the methyltransferase METTL3 oncogene has been shown to increase methylation of pri-miR-1246 to enhance maturation of pri-miR-1246." (PMID 36340774, 2022). "One of the main proteins in m6A, METTL3, is known to regulate apoptosis by targeting Bcl-2 in different types of cancer." (PMID 36012529, 2022). "The expression profiles of METTL3 in pan-cancer indicate that METTL3 is upregulated in various cancers." (PMID 36614956, 2022). "High expression of YTHDF1 and METTL3 has been reported to be associated with lower OS in cancer patients, and YTHDF2, YTHDF1 and METTL3 were proved to be associated with sorafenib treatment and anti-PD-1 immunotherapy response in HCC." (PMID 36618420, 2022). "Previous studies have shown that METTL3 is functionally complex, and it plays crucial roles in a variety of tissues/cells and is involved in regulating the tumorigenesis and cancer progression." (PMID 35892080, 2022). "Corroborating its oncogenic function, METTL3 was reported to promote GC proliferation, migration, and invasion by regulating cancer-related pathways." (PMID 36009465, 2022). "The Gene Expression Profiling Interactive Analysis (GEPIA) website (gepia.cancer-pku.cn) showed that YY1 is positively correlated with METTL3 in AML samples from The Cancer Genome Atlas (TCGA) database." (PMID 36424383, 2022). "Second, we also performed the tissue microarray and IHC to detect the expression of METTL3 at the protein level, which was confirmed significantly higher in cancer tissues than that in the corresponding adjacent normal tissues." (PMID 36058919, 2022). "Taken together, m6A methylation by METTL3 plays an important role in aberrant glucose metabolism in cancer cells." (PMID 36289851, 2022). "The expression of METTL3 is significantly up-regulated in most human cancers such as breast cancer, lung cancer, gastric cancer, and liver cancer." (PMID 36232485, 2022). "Although the role of m6A modification in cancer has been extensively reviewed elsewhere, the key functions of METTL3 in various types of cancer and METTL3 as a potential target for cancer therapy have not been highlighted." (PMID 35794583, 2022). "Accordingly, knockdown of Mettl3 resulted in increased expression of pro-apoptotic proteins in several cancer cell lines, emphasizing that METTL3 can function as a negative regulator of apoptosis." (PMID 35350378, 2022). "For example, the m6A modified writer METTL3 exists as an oncogenic gene in some cancer types such as leukemia, breast cancer and liver cancer but is a tumor suppressor gene in other cancer types such as glioblastoma and endometrial cancer." (PMID 36360248, 2022). "In colorectal cancer (CRC), METTL3 promotes glycolysis and cancer progression in an m6A-dependent manner." (PMID 36071523, 2022). "The correlations between the expression levels of METTL3 and immune infiltrating levels in cancer were explored using the TIMER database." (PMID 36614956, 2022).
cancer (continued). "In CRC, all readers and most writers and erasers show cancer-promoting effects, except for METTL3, METTL14 and ALKBH5." (PMID 35945641, 2022). "Depletion of METTL3 significantly enhanced the sensitivity of cancer cells and murine xenograft models to DNA damage-based therapies, such as chemotherapy drugs or radiation." (PMID 36446846, 2022). "The results showed that the expression of EGFR and METTL3 were all increased compared with paired normal intestinal mucosa adjacent to cancer." (PMID 36347844, 2022). "Other groups reported the important function of METTL3 and its m6A-modified targets in various cancer types." (PMID 36183833, 2022). "Recently, METTL3 was shown to have a positive effect on EGFR levels in cancer cells through translational regulation." (PMID 35190939, 2022). "Numerous studies have revealed that METTL3 promotes the proliferation of cardiomyocytes, smooth muscle cells, primary myoblasts in mice and also a variety of cancer cells." (PMID 35327170, 2022). "Accumulating evidence suggests that m6A writers, in particular METTL3, play a role in promoting glucose turnover in cancer cells." (PMID 36289851, 2022). "Two “writer” genes, METTL3 and METTL14, were shown to have opposing expression patterns in cancers compared to normal indicating that METTL3 and METTL14 functioned as a complex regulator in STAD." (PMID 36620557, 2022). "Our results indicate that METTL3 expression is correlated with MMR gene expression in all types of cancers and correlated with the TMB, MSI, neoantigen loads, and immune checkpoint gene expression in certain cancer types." (PMID 36614956, 2022). "By analyzing the TIMER database, the expression profiles of METTL3 across various cancer types and their corresponding normal tissues were determined." (PMID 36614956, 2022). "Altogether, these findings reveal that METTL3 protects telomeres by catalyzing m6A modification on TERRA, indicating that inhibition or deletion of METTL3 is potentially a new avenue for ALT cancer therapy." (PMID 36399511, 2022). "Conversely, knockout of METTL3 cancer cells led to a decline in glucose consumption, along with reduced ATP and lactate synthesis." (PMID 36289851, 2022). "The angiogenesis process, especially the proliferation of human umbilical vein endothelial cell (HUVEC) and tube formation, was correlated with overexpressed METTL3, subsequently promoting the invasion and distant migration of cancer cells." (PMID 33879256, 2021). "Elevated METTL3 level in cancer cells increases m6A modification in YAP mRNA transcripts which are recognized by m6A readers YTHDF1 and YTHDF3 that are also upregulated in NSCLC cells." (PMID 33814008, 2021). "A high m6A level induced by upregulated METTL3 was responsible for the upregulation of ERRγ with metabolic reprogramming in chemoresistant cancer cells." (PMID 34745970, 2021). "This study revealed the powerful function of METTL3 not only in enhancing the m6A modification pathway in the nucleus but also in facilitating oncogene translation in the cytoplasm, which regulates cancer cell growth, survival, and invasion." (PMID 34315512, 2021). "METTL3, METTL14 and WTAP are the main partners of “writers” belonging to m6A modulators, of which METTL3 is the primary catalytic subunit and has proved essential in promoting metastasis in several cancers." (PMID 33563300, 2021). "Recent studies have shown elevated METTL3 promotes EMT in cancers, and several EMT-TFs (such as Snail and Slug) are key molecules of EMT." (PMID 33563300, 2021). "For instance, overexpression of METTL3 in AML significantly inhibits cancer cell differentiation and apoptosis via activating PI3K/AKT pathway." (PMID 34484284, 2021). "In summary, loss-of-function screens of cancer cell lines support the biological importance of several METTLs, notably METTL1, METTL3, METTL14, METTL16 and METTL17, in promoting cancer cell growth and survival." (PMID 34285249, 2021).
cancer (continued). "In hypopharyngeal squamous cell carcinoma (HPSCC), malignant tumors with one of the worse prognoses, METTL3 confers radioresistance by promoting the stability of circCUX1." (PMID 34315512, 2021). "In most cases, METTL3 has been reported as an oncogene that promotes the occurrence and progression of a variety of cancers, including hematopoietic malignancies and solid tumors, by depositing m6A modifications on key transcripts." (PMID 34336690, 2021). "Increased METTL3 and m6A-mediated upregulation of estrogen receptor related receptors γ (ERRγ) was shown to trigger chemoresistance in cancer cells." (PMID 33814008, 2021). "METTL14 plays a similar role in cancer as that of METTL3; it promotes DGCR8 to recognize and bind m6A-modified pri-miRNAs, which further mediates miRNA maturation." (PMID 34108450, 2021). "Correspondingly, up-regulated CCND1 and suppressed cancer aggressiveness were observed after METTL3 RNAi." (PMID 34178650, 2021). "METTL3 mainly promotes cell proliferation, invasion, migration, metabolic reprogramming, and drug resistance in cancer." (PMID 33879256, 2021). "Along with the development of targeted inhibitors of epitranscriptomic modulators (e.g., METTL3) now entering clinical trials, the field holds significant promise for treating these abundant cancers." (PMID 34209046, 2021). "METTL3 is a methyltransferase that can modulate the initiation and progression of various types of cancers." (PMID 34666602, 2021). "In this type of cancer, the m A methyltransferase METTL3 oncogene has been shown to increase methylation of pri-miR-1246 to enhance maturation of pri-miR-1246." (PMID 35047553, 2021). "The recent rediscovery of m6A is due to its crucial role in the growth and progression of many types of cancer, where different components have an alternated expression, in particular METTL3." (PMID 34530916, 2021). "For instance, METTL3 appears to enhance translation of its binding RNA transcripts by relieving ribosome stalling in cancer cells." (PMID 34262022, 2021). "Most recently, METTL3 has emerged as an attractive therapeutic target for treatment in different types of human cancer." (PMID 34514103, 2021). "The METTL3 expressions in cancer tissues and cells were detected with extensive analysis of its correlation with clinical baseline data." (PMID 34666602, 2021). "Consistently, the controversial role of METTL3 has also been reported in other cancer types by different groups, such as glioblastoma 47,48." (PMID 33456561, 2021). "METTL3-mediated m6A modification of EZH2 mRNA increased migration and invasion level in NSCLC, and Simvastatin generated anti-cancer effects by downregulating METTL3 expression." (PMID 33808751, 2021). "METTL3 has also been found upregulated in bladder cancer (BCa) which promoted proliferation, migration and suppresses the apoptotic cancer cell death." (PMID 33814008, 2021). "In patientswith high-risk cancer, ZC3H13 expression is upregulated, while the expression of METTL3, KIAA1429, YTHDF1 and YTHDF2 is downregulated." (PMID 34246319, 2021). "In human cancer, an increasing number of reports have found that METTL3 can participate in the tumorigenesis process." (PMID 33531456, 2021). "Herein, we provided the first evidence to show that the METTL3/SNHG1/miR-140-3p/UBE2C axis plays a crucial role in cancer progression and the immune response in human pan-cancer." (PMID 34858987, 2021). "In clear cell renal cell carcinoma (ccRCC), METTL3 and METTL14 constitute a risk signature for use in prognostics, because they are significantly enriched in cancer-related pathways, including the Wnt/β-catenin signaling pathway." (PMID 34315512, 2021). "When the expression level of METTL3 is upregulated, it enhances the proliferation, migration, and invasion of cancer cells in vitro and the growth of tumors in vivo." (PMID 34957092, 2021). "METTL3, the catalytic component, is the most important part of methyltransferase complex and plays a crucial role in cancers." (PMID 33867838, 2021).